CD44 (CD44 molecule (IN blood group))
Diseases named in the same sentence as CD44 in open-access papers (continued):
Sharing a sentence is not in itself a finding about the gene and the disease.
breast carcinoma (continued). "Human breast cancer cell lines contain CD44+CD24–/lowESA+ cells that exhibit characteristic stem cell features like anchorage-independent growth at clonal densities, the ability to reconstruct the parental cell fractions, along with enhanced tumorigenicity in mice." (PMID 22901246, 2012). "In addition, CD44/CD24 has been applied as a criteria marker for determining the stem-like CIC among breast cancer cell lines treated with various factors to favor the growth of or transition to stem-like cells." (PMID 21935375, 2011). "Therefore, the subset of CD44+/CD24−/low/ESA+ has been recognized as being breast cancer initiating cells (CIC)." (PMID 21935375, 2011). "CD44+/CD24−cells have been firstly proposed to exhibit CSC properties in breast cancer." (PMID 21304586, 2011). "Moreover, the CD44+/CD24- phenotype was found to correlate with the more aggressive basal-like subtype of breast cancer." (PMID 21957977, 2011). "However, activation of ATM signaling was significantly increased in CD44+/CD24−or low cells compared to non- CD44+/CD24−or low cells in both from breast cancer cell lines and primary human breast cancer cells." (PMID 21935375, 2011). "Moreover, we identify a novel tumor promoting mechanism of these cells that is enhanced upon exposure to PGE2: the ability to secrete factors (such as IL-6) that are essential for the expansion of CD44+/CD24−/EpCAM+ breast cancer cells." (PMID 21957456, 2011). "The interaction of CD44 and HA activates RhoA signals and Rho kinase, enhances serine/threonine phosphorylation on Gab-1 (Grb2-associated binder-1), induces PI3K activation, triggers the PI3K/Akt pathway, and is involved in the progression of breast cancer." (PMID 21294926, 2011). "CD44+/CD24-/low breast cancer cells have tumour-initiating properties with stem cell-like features." (PMID 23508738, 2011). "This study aimed to determine if CD44 knockdown caused BCSCs to differentiate into breast cancer non-stem cells (non-BCSCs)." (PMID 22152097, 2011). "In the current studies, we utilized CD236/CD44/CD24 for isolation of CIC of breast cancer cells based on previous studies showing that ESA+/CD44+/CD24−or low breast cancer cell subset from human breast cancer tissue and breast cancer cell lines is more tumorigenic and more stem-like behavior." (PMID 21935375, 2011). "For example, a large study that examined a 186-gene invasiveness signature generated from CD44/CD24−/low tumorigenic breast-cancer cells or normal breast epithelium, indicated its strong association with a reduced overall survival and a propensity of tumor to metastasize." (PMID 24212957, 2011). "Another antibody against CD44, called P245, inhibited growth of breast cancer xenograft in mice." (PMID 21541039, 2011). "Our results suggest that specific CD44 isoforms may have distinct roles in different breast cancer subtypes and can potentially be involved in specific oncogenic signaling pathways." (PMID 21957977, 2011). "This prompted several attempts to characterise CD44+CD24-/low cells in primary breast carcinomas." (PMID 22112299, 2011). "Additionally, following a low dose of radiation an increase in stem-like cells in the irradiated breast cancer cell population was detected by flow cytometric analysis utilizing the CD44/CD24 criteria for CIC." (PMID 21935375, 2011). "However, it has been previously reported that the expression of CD44 potentially prevents breast cancer cells from metastasizing." (PMID 21749678, 2011). "In highly metastatic basal-like MDA-MB-231 breast cancer cells, our group has shown that metformin treatment dynamically suppresses the CD44+/CD24−/low CSC phenotype via transcriptional repression of the EMT machinery including Transforming Growth Factor-β1, ZEB, TWIST and SLUG (SNAIL2)." (PMID 22203527, 2011). "Fractional radiation also increased the CD44+/CD24−/low− subset in breast cancer cell lines." (PMID 21935375, 2011).
breast carcinoma (continued). "For example, SDF1α is a growth factor secreted by myofibroblasts that promotes breast cancer cell growth as well as expansion of CD44+/CD24− cells, and may be upregulated by PGE2." (PMID 21957456, 2011). "In contrast, breast cancer CD44+/CD24−/low CIC have dysregulated innate immune responses featuring dysfunctional virus recognition caused by impaired trafficking of TLR9 and cofactor MyD88 and the absence of TLR2, having a deleterious impact on TLR pattern recognition receptor signaling." (PMID 21079774, 2010). "Similarly, the JIMT-1 breast cancer patient pleural effusion explant derived cells were positive for CD44 and Oct3/4 respectively." (PMID 21079774, 2010). "Interestingly, a subpopulation of CD44 high/CD24 low CSC-like disseminated breast cancer cells were found in pleural effusions." (PMID 24281178, 2010). "In a mammosphere assay, MCF-7-SLUG cells formed more and larger mammospheres compared to MCF-7-pQXIN cells, suggesting SLUG may confer a CSC phenotype to luminal breast cancer cells and these putative CSCs are phenotypically CD44+/CD24+." (PMID 20691079, 2010). "It is therefore likely that CD24−/low/CD44+ cells in breast cancer cell lines may behave in a manner similar to TICs." (PMID 19997106, 2010). "Similarly, breast cancers with PD/SD had higher percentage of CD44+/CD24−cancer cells than those with PR/CR (35.0%±9.13% vs. 1.56±0.33%, p<0.001)." (PMID 21187973, 2010). "To examine whether CD24−/low/CD44+ cell populations exist in various types of breast cancer cell lines, we analysed the expression of these surface markers in eight breast cancer cell lines by FACS analysis." (PMID 19997106, 2010). "CD44+/CD24- have been identified as markers for human breast cancer stem cells." (PMID 21044318, 2010). "It has been observed that basal-like breast cancers might be enriched with CD44+/CD24− cells, and an overlap between CD44+/CD24− cells and ALDH1-positive cell populations were described." (PMID 20010944, 2010). "We showed that several breast cancer cell lines have a small population of CD24−/low/CD44+ cells in which TICs may be enriched, and confirmed the properties of TICs in a xenograft model." (PMID 19997106, 2010). "Breast CSCs, or tumor-initiating cells, can be isolated by the immuno-sorting of breast cancer cells that express the hyaluronian receptor CD44, a gene that is overexpressed in basal-like tumors and lack the expression of CD24, an endogenous inhibitor of the chemokine receptor CXCR." (PMID 24281098, 2010). "The alterations and characteristics of MCF-7-14 cells, especially nuclear β-catenin and CD44 upregulation, may characterize invasive cell populations in breast cancer." (PMID 20696077, 2010). "Furthermore, the prevalence of CD44+CD24- cells in breast cancer patients indicates a link between high numbers of stem-like cancer cells and metastasis." (PMID 21067584, 2010). "In MDA-MB-231 cells, PROCR and ESA, instead of the widely used breast cancer stem cell markers CD44+/CD24-/low and ALDH, could be used to highly enrich cancer stem/progenitor cell populations which exhibited the ability to self renew and divide asymmetrically." (PMID 20027313, 2009). "However, numerous other studies have suggested that CD44 promotes invasiveness of breast cancer cells." (PMID 19602265, 2009). "In this regard, one study confirmed a putative stem cell phenotype in disseminated tumor cells (DTCs), and another study showed that the majority of early DTCs detected in the bone marrow of breast cancer patients with a CD44+/CD24- phenotype correlated with a higher prevalence of bone metastases." (PMID 19589136, 2009). "Nineteen breast cancer cells lines were initially screened for their expression of CD44 and CD24." (PMID 19906290, 2009).
breast carcinoma (continued). "CD44 represents a proteoglycan-rich surface protein that is involved in numerous signaling mechanisms and contributes to processes such as cell adhesion, migration and invasion and thus, the characterization of a distinct population of highly tumorigenic breast cancer cells revealed CD44 expression." (PMID 19751512, 2009). "Interestingly, CD44 was also found to be a positive marker of tumour-initiating cells in different types of tumours, including breast cancers." (PMID 19240712, 2009). "At least one study has confirmed a putative stem cell phenotype in DTCs, and another study has shown that the majority of early DTCs detected in the BM of breast cancer patients with a CD44+/CD24- phenotype correlated with a higher prevalence of bone metastases." (PMID 19664291, 2009). "Basal-B lines were characterized by markers associated with aggressive tumor features, including PLAT (plasminogen activator) and TGFB1, as well as marker phenotypes associated with normal breast and breast cancer progenitor/stem cells (MUC−/CALLA+; CD44+/CD24−/low; and ITGB3(CD61)+)." (PMID 19582160, 2009). "CD44-targeted therapy of breast cancer might therefore require a continuous administration of the P245 mAb, as is the case for other antibody-based therapies, such as with the anti-HER2 mAb (trastuzumab)." (PMID 19240712, 2009). "In breast cancer, CD44+/CD24- population harbors stem cell properties." (PMID 19751508, 2009). "In breast cancer, the role of CD44 in cell proliferation is still unclear." (PMID 19240712, 2009). "Similar seedpairing in miRNA families indicates that they may function through the same pathways and share mRNA targets – such as CD44, identified as a target of miR-373 and known to correlate with survival in breast cancer patients." (PMID 19432961, 2009). "Based on our results, using breast cancer cell lines to target CD44+/CD24-/ESA+ cells for drug discovery offers a highly promising, reproducible, and cost-effective means to identify therapies that prevent self-renewal or force depletion of tumorigenic breast cancer stem-like cells." (PMID 18366788, 2008). "In breast cancer, previous analysis identified CD44+CD24− cells as both clonogenic and tumorigenic." (PMID 18268494, 2008). "To evaluate whether tumorsphere formation indeed mirrors tissue regeneration in our breast cancer cell lines, we assayed the percentages of CD44+/CD24-/ESA+ cells in maturing tumorspheres." (PMID 18366788, 2008). "Hence, similar to the case in primary tumors, these tumorigenic breast cancer stem-like cells are enriched 100-fold in the CD44+/CD24-/low/ESA+ fraction across multiple cell lines." (PMID 18366788, 2008). "Breast cancer cells with a CD44+/CD24- phenotype have been suggested to have tumor-initiating properties with stem cell-like and invasive features, although it is unclear whether their presence within a tumor has clinical implications." (PMID 18559090, 2008). "We could thereby demonstrate an association between the presence of CD44+/CD24- tumor cells and a basal-like subgroup of breast cancer." (PMID 18559090, 2008). "Interestingly, the HER2+ tumor subtype, generally considered an aggressive form of breast cancer, displayed a low frequency of tumors containing CD44+/CD24- cells and was in fact often positive for the CD44-/CD24+ phenotype." (PMID 18559090, 2008). "One tumor had distinct features of EMT and gave rise to cell lines that contained a distinct CD44+/CD24-/low population that may correlate with human breast cancer stem cells." (PMID 18394172, 2008). "Metastatic tumor cells may have a more stem cell-like phenotype, as indicated by enrichment of the CD44+/CD24- phenotype in bone marrow micrometastasis of breast cancer patients." (PMID 18559090, 2008). "Recent reports suggested heterogeneity in human breast cancer stem cells that express CD44." (PMID 18241344, 2008).
breast carcinoma (continued). "To determine whether Brca1 cell lines contain a distinct population of cancer stem cells, we examined expression of cell surface markers previously assigned to human breast cancer stem cells, namely CD44 and CD24." (PMID 18241344, 2008). "Given the reported similarity between murine breast and prostate stem cells and the recent identification of a CD44+CD24− subpopulation of breast cancer cells that have an increased tumorigenic capacity, we sought to identify and characterise CD44+CD24− cells in human prostate cell lines." (PMID 18268494, 2008). "Variable degrees of expression of MUC1 and CD44 (exons 8-11) were detected in normal peripheral blood, rendering these genes non-specific for epithelial cells and therefore unsuitable for use as markers to detect breast carcinoma cells." (PMID 9579823, 1998). "Thus, for example, CSC from breast cancer express CD44, CD49f, CD133, ALDH1, and Sox2; prostate CSC are known to express CD133, CD44, integrin α2β1, CD49f, ALDH1, EZH2, and SOX2; while colon CSC express CD133, CD44, CD49f, and ALDH1, showing an overlap in the CD133, CD44, CD49f, and ALDH1 markers." (PMID 39859345, 2025). "Thus, GRP78, through its interaction with client proteins in the ER, could cotraffic with them to the cell surface, as exemplified by GRP78 interacting with the transmembrane protein CD44 in the ER as well as on the cell surface of breast cancer cells." (PMID 40699920, 2025). "Indicates that CD44 palmitoylation could be a new therapeutic target for breast cancer." (PMID 40977744, 2025). "Thus, hypoxia regulates CD44 expression via HIF-1α in breast cancer and gastric cancer." (PMID 38247821, 2024). "Notably, the absence of breast cancer stem cell-associated gene expression, particularly the CD44+CD24- phenotype was observed with salinomycin treatment, further emphasizing its specific action against CSCs." (PMID 39403386, 2024). "Additionally, almost all murine GBM CTCs expressed Olig2, and 40% expressed CD133; CSC markers are detected on a fraction of CTCs in a variety of types of cancer, including breast cancer (CD44), colorectal cancer (LGR5), non-small cell lung cancer (NSCLC) and ovarian cancer (BMI1, CD133, ALDH1)." (PMID 38609981, 2024). "Therefore, it is also speculated that RHAMM and CD44 cooperatively contribute to chemoresistance of breast cancer." (PMID 39518040, 2024). "To test if the role of FGF2 could shift from promoting proliferation to inducing a stem-like state in FGFR1 amplified cells, we next investigated the effect of FGF2 on cancer stemness-like traits using FACS analysis for ALDH and CD44 (two known markers of breast cancer stemness)." (PMID 38553760, 2024). "Moreover, HA also serves as a tumor-targeting ligand that recognizes CD44 overexpression on various tumor cell membranes such as prostate cancer, breast cancer, and non–small cell lung cancer, and thus HA-coated NCs can also actively target to tumors after systemic administration." (PMID 39146021, 2024). "Furthermore, CD44 has been demonstrated to play a role in the development of drug resistance in breast cancer cells treated with Trastuzumab, Lapatinib, and Tamoxifen, therefore targeting CD44 in conjunction with other potential drug targets remains of high interest." (PMID 39268460, 2024). "Furthermore, LYVE-1 has no variants, whereas CD44 has several variants and CD44-positive capillaries are found in various cancers, including breast cancer." (PMID 39273689, 2024). "Interestingly, the HA receptor CD44 is highly expressed in the subpopulation of breast cancer cells with stem cell potential, and HA-coated particles could be used as a vehicle to reach such an aggressive population of cells." (PMID 37568628, 2023).
breast carcinoma (continued). "Moreover, the CD44+/CD24− phenotype is most common in basal-like breast cancer, which may indicate that this type of cancer has a higher percentage of CSCs." (PMID 37492743, 2023). "Moreover, a recent study proposed that KYNU could be a potential transcriptional target of CD44-downstream signaling promoting tumor cell invasion, cellular migration and survival, and metastasis in breast cancer." (PMID 36986469, 2023). "On its own, CD44 is a highly diversified transmembrane glycoprotein consisting of several isoforms extensively expressed on cancerous cells such as lung, renal, gastric, colon, pancreatic, and breast cancers, leading to numerous roles in cell adhesion, proliferation, and signaling." (PMID 37399498, 2023). "The CD44+ rare cell and subtype denotes improvement in detection of residual cancer disease and may provide an objective and alternative measure of disease burden in early-stage breast cancer." (PMID 36100762, 2023). "Also, CD NPs demonstrated the highest anti-CSC and proapoptotic activities in mammary tumor, as evidenced by the minimum percentage of CD44+-stained cells (20.26 ± 2.19%) and the maximum percentage of caspase 3+-stained cells (95.71 ± 1.49%) compared to ZD NPs and Fu." (PMID 36864097, 2023). "However, solely 7.4% of MCF-7/HER2 breast cancer cells were CD44+/CD24−/low." (PMID 35562905, 2022). "In addition, CD44 is used for diagnosing breast cancer in different stem cells (BCSCs)." (PMID 36560548, 2022). "Additionally, the upregulation of HA-mediated motility receptor (RHAMM) promotes breast cancer progression, and our engineered 3D model could be used for investigating the role of RHAMM in CD44-positive breast cancer cell progression and metastasis." (PMID 35198956, 2022). "Additionally, FUCA1 could inhibit intercellular adhesion of breast cancer cells though down-regulating their CD44, CD15, and matrix metalloproteinases (MMP) -9 expression." (PMID 36046653, 2022). "Therefore, identifying and inhibiting an ideal and specific CD44 interactor involved in the CD44‐mediated protumour role might provide a solution and new options for advanced breast cancer therapy." (PMID 35090088, 2022). "In addition, the nano-carriers had good biosafety and could significantly internalize within 24 h of incubation due to CD44-mediated endocytosis of the nanohydrogels in human breast cancer cells MCF-7." (PMID 36091467, 2022). "Additionally, CD44 upregulation in breast cancer has been correlated with a higher tumor grade." (PMID 36289750, 2022). "Besides, the phenotypic CD44+/CD24− subpopulation of breast cancer cells are also termed as BCSCs." (PMID 36042208, 2022). "Moreover, the overexpression of CD44 promoted breast cancer migration and invasion." (PMID 36289750, 2022). "Interestingly, mammospheres formed from patient-derived primary breast tumors were enriched in breast cancer stem-like cells with the phenotype CD44+/CD24-/low and exhibited a relatively more number of large spheres when compared to the normal breast stem cells." (PMID 36504339, 2022). "Besides, in RNF31 knocking down background, RNF31 overexpression could decrease the proportion of CD44+/CD24- breast cancer cells." (PMID 36581998, 2022). "Therefore, targeting the CD44+/CD24− population could be considered one of the promising therapeutic therapies for breast cancer patients." (PMID 35631492, 2022). "Consequently, these scaffolds may not be suitable for studying CD44/HA-mediated signaling pathways in the context of CD44-positive breast cancer development." (PMID 35198956, 2022). "Additionally, the functional analysis demonstrates that the CD44-Stat3 axis is closely associated with the EMT process, which participates in the resistance to radiation in various tumors, such as NPC, lung cancer and breast cancer." (PMID 36678534, 2022).